BACE1 (beta-secretase 1)
Diseases named in the same sentence as BACE1 in open-access papers (continued):
Sharing a sentence is not in itself a finding about the gene and the disease.
Alzheimer disease (continued). "No previous studies have reported on the anti-Alzheimer’s disease property of CSA, and this study is the first to report its anti-Alzheimer’s disease potential through the inhibition of cholinesterases and BACE-1 activities." (PMID 38066118, 2023). "SIGNIFICANCE STATEMENT BACE1 is widely recognized as a therapeutic target for treating Alzheimer’s disease patients." (PMID 37536983, 2023). "These phytocompounds were docked with the BACE-1 protein, which is the major target for Alzheimer’s disease." (PMID 37367915, 2023). "PE has been suggested as a potential treatment for Alzheimer’s disease thanks to the inhibition of the beta-site amyloid precursor protein cleaving enzyme-1 (BACE1)." (PMID 37623721, 2023). "Two potential target genes, GSK3B and BACE1, have been deemed possible candidates as disease-modifying agents for Alzheimer’s disease due to their involvement in amyloid-beta and tau production, as well as their ability to enhance cognitive functions." (PMID 37444065, 2023). "A PEG-based polymeric formulation was conjugated with galactose to enhance brain delivery of anti-BACE1 siRNA against Alzheimer’s disease, based on the observation that D-glucose and D-galactose are both substrates of GLUT1." (PMID 36770817, 2023). "The highest enzyme inhibitory activity was observed in β-secretase (BACE-1) (54.61% inhibition at the extraction concentration of 8 mg/mL), the β-amyloid formation enzyme, which is a drug target for Alzheimer’s disease (AD) treatment." (PMID 37241861, 2023). "β-site amyloid precursor protein-cleaving enzyme 1 (BACE1) is considered a therapeutic target to combat Alzheimer’s disease by reducing β-amyloid in the brain." (PMID 37569661, 2023). "BACE1 is found to be a crucial target protein in the identification of novel strategies to minimize and prevent Alzheimer's disease." (PMID 38106650, 2023). "In this research, our approach is to analyze the effect of phytochemicals in Cannabis sativa on multiple culprit enzymes in Alzheimer’s disease, such as AChE (Acetylcholinesterase), BChE (Butyrylcholinesterase), γ-secretase, and BACE-1." (PMID 36771595, 2023). "BACE1’s involvement in the amyloidogenic pathway offers the potential to target Alzheimer’s disease." (PMID 37444065, 2023). "The application of in silico study in drug discovery has been explored in another study by our research group entitled “Allostery Inhibition of BACE1 by Psychotic and Meroterpenoid Drugs in Alzheimer’s Disease Therapy”." (PMID 37958503, 2023). "β-amyloid cleaving enzyme 1 (BACE1) is regarded as an important target of drug design toward the treatment of Alzheimer’s disease (AD)." (PMID 37375328, 2023). "Atabecestat, a potent brain penetrable BACE1 inhibitor that reduces CSF amyloid beta (Aβ), was developed as an oral treatment for Alzheimer’s disease (AD)." (PMID 37658353, 2023). "The β-secretase BACE1 (β-site APP cleaving enzyme) is a major drug target in Alzheimer’s disease (AD)." (PMID 36810097, 2023). "Proteolytic processing of amyloid protein precursor by β-site secretase enzyme (BACE1) is dependent on the cellular lipid composition and is affected by endomembrane trafficking in dementia and Alzheimer's disease (AD)." (PMID 37744400, 2023). "For example, the Alzheimer Disease (AD)-associated proteins APP, BACE1, Nicastrin, Tau, APOE and TREM2 all have several N- and O-glycosylations." (PMID 37201132, 2023). "Here, we show that longitudinal measures of CSF Ng, BACE1, and Ng/BACE1 levels are consistent traits across the A/T/N stages of the Alzheimer’s disease continuum." (PMID 36262371, 2022). "As a proof‐of‐concept, we explored the potential of AAV‐delivered VHH to inhibit BACE1, a well‐characterized target in Alzheimer’s disease." (PMID 35352880, 2022). "BDNF-AS promotes BACE1 expression and Alzheimer’s disease progression through the competitive binding of miR-9-5p." (PMID 35743271, 2022).
Alzheimer disease (continued). "β-site APP-cleaving enzyme 2 (BACE2) is a homolog of BACE1, which is considered as the most promising therapeutic target for Alzheimer’s disease (AD)." (PMID 35110536, 2022). "In a study exploring the advantages of using miRNAs as a therapeutic target for Alzheimer’s disease, researchers found a group of miRNAs that regulate BACE-1 (β Secretase 1) in different ways." (PMID 35327979, 2022). "BDNF anti-sense RNA (BDNF-AS) promotes BACE1 expression and Alzheimer’s disease progression through the competitive binding of miR-9-5p." (PMID 35743271, 2022). "Beta-site amyloid-precursor-protein cleaving enzyme 1 (BACE1) has for several years been considered a potential drug target for therapeutic intervention in Alzheimer's Disease (AD)." (PMID 35936777, 2022). "BACE1 (β-site of amyloid precursor protein cleaving enzyme) is an enzyme involved in Alzheimer’s disease pathogenesis." (PMID 35447894, 2022). "Flavonoids are promising natural products with neuroprotective potential that prevent or slow the progression of Alzheimer disease via the inhibition of key enzymes such as AChE, BChE and BACE-1 (Beta-site APP Cleaving Enzyme-1)." (PMID 36295014, 2022). "Blockers of the enzyme BACE-1 induce, in neurons and glial cells, decreased levels of Aβ, the key peptide of the Alzheimer’s disease." (PMID 35052785, 2022). "The current subsection explains the in vitro, in vivo, and in silico studies performed for natural products and bioactive molecules derived from them in the management of Alzheimer’s disease via the inhibition of BACE-1 enzymes." (PMID 35956919, 2022). "The β-secretase BACE1 cleaves APP at the N-terminus of the Aβ domain, which is the first step in the formation of pathogenic Aβ in Alzheimer’s disease." (PMID 35900966, 2022). "All clinical BACE1-inhibitor trials for the treatment of Alzheimer's Disease (AD) have failed due to insufficient efficacy or side effects like worsening of cognitive symptoms." (PMID 35936777, 2022). "As a method of treatment, AAV-mediated delivery of Nbs into the brain has also been evaluated, namely for the Nb targeting BACE1 (beta-secretase 1), a target in Alzheimer’s disease." (PMID 36426363, 2022). "PrPC additionally controls the expression of the amyloid precursor protein APP and of the Aβ generating enzyme BACE1, and regulates the levels of Aβ, whose accumulation is a central event in Alzheimer’s disease." (PMID 35962130, 2022). "Tasiamide B is also a β-secretase 1 (BACE1) inhibitor, with an IC50 value of 0.19 uM against BACE1, has the potential to target Alzheimer’s disease, as BACE1 is involved in abnormal β-amyloid plaque production." (PMID 36500375, 2022). "β-Site Amyloid precursor protein Cleaving Enzyme-1 (BACE-1) was identified over 20 years ago as a key component in Alzheimer disease (AD) pathogenesis." (PMID 35252355, 2022). "BACE1 activity is increased in the brains of individuals with Alzheimer’s disease and Down syndrome." (PMID 36251052, 2022). "Polyphenols derived from green and black tea, as well as Smilax china L. (Smilacaceae), are effective BACE-1 inhibitors, which aids in slowing the advancement of Alzheimer’s disease." (PMID 35651632, 2022). "S-Palmitoylation of BACE1 and its role in Alzheimer’s disease was studied by developing a gene knock-in transgenic AD mice, where the cysteine residues of S-palmitoylation were changed to alanine residues." (PMID 36158539, 2022). "Cerebrospinal fluid (CSF) β-site amyloid precursor protein cleaving enzyme 1 (BACE1), neurogranin and the neurogranin/BACE1 ratio are proposed markers for Alzheimer’s disease." (PMID 36262371, 2022). "VHH and blood‐brain‐barrier (BBB)‐crossing AAV‐based vectors are combined to achieve highly‐specific, long‐term BACE1 inhibition in a mouse model of Alzheimer's disease (AD)." (PMID 35352880, 2022).
Alzheimer disease (continued). "BACE1 encodes a member of the peptidase A1 family of aspartic proteases, and both BACE1 expression and activity are elevated in the aging brain and Alzheimer’s disease (AD), as well as in response to oxidative stress and inflammation." (PMID 36466876, 2022). "There is evidence that AzB as well as MB suppresses the expression of App and Bace1, which are responsible for Tau aggregation and the development of Alzheimer’s disease and inhibit caspases." (PMID 35890114, 2022). "β-Secretase1 (BACE1) catalyzes the rate-limiting step in the generation of amyloid-β peptides, that is, the principal component involved in the pathology of Alzheimer’s disease (AD)." (PMID 35402415, 2022). "β-Site amyloid precursor protein (APP) cleaving enzyme-1 (BACE1) is the major described β-secretase to generate Aβ peptides in Alzheimer’s disease (AD)." (PMID 35235058, 2022). "The β-site Amyloid precursor protein Cleaving Enzyme 1 (BACE1) is an extensively studied therapeutic target for Alzheimer’s disease (AD), owing to its role in the production of neurotoxic amyloid beta (Aβ) peptides." (PMID 35562959, 2022). "Evidence suggests that β-secretase (BACE1), which cleaves Amyloid Precursor Protein (APP) to form sAPPβ and amyloid-β, is elevated in Alzheimer's disease (AD) brains and biofluids and, thus, BACE1 is a therapeutic target for this devastating disease." (PMID 36056033, 2022). "β‐site amyloid precursor protein cleaving enzyme‐1 (BACE1) research has historically focused on its actions as the β‐secretase responsible for the production of β‐amyloid beta, observed in Alzheimer's disease." (PMID 35119166, 2022). "BACE1 activity is increased in brains of patients with Alzheimer’s disease (AD) and mild cognitive impairment (MCI) and plasma levels of BACE1 appears to reflect those in the brains." (PMID 35275540, 2022). "For example, the beta-site amyloid precursor protein cleaving enzyme 1 (BACE1) is accumulated in Alzheimer’s disease (AD) patients and is studied as a therapeutic target." (PMID 35280983, 2022). "Several reports have indicated an increase in BACE1 expression and activity under oxidative stress in neuronal cells, and increased BACE1 expression correlates with oxidative lipid modifications in Alzheimer’s disease patient tissue." (PMID 34679674, 2021). "Our results indicate that Aβ peptides depositing specifically in the insoluble pools of Alzheimer’s disease brain have approximately equal amounts of BACE-1 cleaved Aβ (Asp-1 as the N-terminus) and ragged N-terminus peptide (Phe-4 residue)." (PMID 33928245, 2021). "In a similar approach, Lamp2b was fused with the rabies virus glycoprotein, a neuron‐specific peptide to deliver an siRNA against beta‐secretase 1 (BACE1), a precursor for Alzheimer's disease." (PMID 33751579, 2021). "The aberrant expression of these molecules has been related with numerous neurological syndromes and mainly in subjects with Alzheimer’s disease, which emphasizes the importance of regulating the catalytic activity of BACE1 in this disease." (PMID 33668203, 2021). "When siRNA-BACE1, a therapeutic target for Alzheimer’s disease, was loaded into these sEVs, the modified sEVs significantly reduced the mRNA and protein levels of BACE1 in mouse nerve cells." (PMID 34094979, 2021). "The powerful protein (62%) and mRNA (60%) inhibition of BACE1 (a therapeutic target for Alzheimer's disease) demonstrated the therapeutic potential of exosome-mediated siRNA." (PMID 34522219, 2021). "Enhanced axonal regeneration has been observed in mice with deletion of the sheddase beta-secretase (BACE1), a transmembrane aspartyl protease that has been studied in the context of Alzheimer’s disease." (PMID 33722254, 2021). "For example, in Alzheimer’s disease, the post-transcriptional regulation of BACE1 involves miR-485-5p, and the specific antisense transcription of BACE1 forms lncRNA-BacE1-As, which compete with lncRNA-Bace1-As to bind to the binding sites of related mRNAs." (PMID 34977024, 2021).
Alzheimer disease (continued). "Studies have demonstrated greater BACE1 activity and protein concentration in Alzheimer’s disease compared with elderly health controls and patients with mild cognitive impairment compared to controls or Alzheimer’s disease patients." (PMID 33578866, 2021). "On the other hand, potential benefits of miR-124 upregulation were referred in Alzheimer’s disease through negative regulation of BACE1 expression." (PMID 34200161, 2021). "After the continued failure of β‐secretase (BACE1) inhibitor clinical trials in prodromal as well as mild‐to‐moderate Alzheimer's disease (AD), they are shifting to further earlier or asymptomatic stages." (PMID 33749160, 2021). "A lot of studies showed that total protein and activity of BACE1 increase in area of brain which affected by Alzheimer disease and indicated that abnormal activity of BACE1 had a functional role in Alzheimer pathogenesis." (PMID 33586916, 2021). "Overall, research on CSF BACE1 activity and its protein concentration has given varied results for Alzheimer’s disease patients." (PMID 33578866, 2021). "In a case–control and longitudinal study at a specialized memory clinic, where the patients were followed for 3–6 years, CSF BACE1 activity was significantly higher in Alzheimer’s disease patients than in normal control subjects." (PMID 33578866, 2021). "BACE1 plays a critical role in the pathophysiology of Alzheimer’s disease, and its rates of activity and concentrations have been found to be elevated in body fluids (such as plasma and CSF) and in the brains of Alzheimer’s disease patients." (PMID 33578866, 2021). "The data on CSF BACE1 protein and its activity are promising and show that these two tests are elevated in Alzheimer’s disease patients compared to elderly health controls." (PMID 33578866, 2021). "Alzheimer’s disease (AD) is implicated in the imbalance of several proteins, including Amyloid-β (Aβ), amyloid precursor protein (APP), and BACE1." (PMID 34577601, 2021). "Beta-site amyloid precursor protein (APP) cleaving enzyme 1, also known as β-secretase (BACE1), has been extensively studied for its role in Alzheimer’s disease." (PMID 33722254, 2021). "The generation of amyloid β-peptides (Aβ) via sequential cleavages of APP by β-secretase (BACE1) and the presenilin/γ-secretase complex is central to the initiation of Alzheimer’s disease (AD)." (PMID 33571524, 2021). "Another study has also shown that a decrease in the expression of miR-29a or miR-29b increases the expression of BACE1 in brain tissue of subjects with Alzheimer’s disease." (PMID 33561007, 2021). "The cell surface receptors, GPCR and the subsequent GPCR related signaling molecule are involved in regulation of BACE1, γ-secretase and eventually affect Tau phosphorylation in Alzheimer’s disease." (PMID 35006431, 2021). "Being the rate-limiting enzyme in the amyloidogenic pathway and playing a large role in the production of the neurotoxic intermediate, Aβ, aberrant BACE1 activity is considered pivotal to Alzheimer’s disease progression." (PMID 34017238, 2021). "siRNA against BACE1, a therapeutic target for Alzheimer’s disease, was loaded into this EV by electroporation and administered to wild-type mice, resulting in the effective knockdown of BACE1." (PMID 34885247, 2021). "Acetylcholinesterase (AChE), butyrylcholinesterase (BChE), and β-secretase (BACE-1) are the key enzymes involved in controlling Alzheimer’s disease (AD) pathology." (PMID 33924574, 2021). "BACE1 is the same enzyme identified for cleavage of the amyloid precursor protein involved in the pathogenesis of Alzheimer’s disease." (PMID 34290711, 2021). "Beta-site amyloid precursor protein cleaving enzyme 1 (BACE1) plays a criticalrole in Alzheimer’s disease (AD) pathogenesis." (PMID 33428703, 2021).
Alzheimer disease (continued). "Despite BACE1 and BACE2 were discovered simultaneously, BACE1 captured first the attention of the scientific community mainly for its role in regulating the formation of cytotoxic Aβ peptides in Alzheimer's Disease (AD)." (PMID 33926496, 2021). "For example, amyloid beta (Aβ) is a major pathological marker in Alzheimer's disease (AD), which is principally regulated by the rate‐limiting β‐secretase (BACE1) cleavage of amyloid precursor protein." (PMID 32827359, 2020). "Tideglusib treatment also decreased levels of beta-secretase 1 (BACE-1) and phospho-tau in cerebral spinal fluid of Alzheimer’s disease patients." (PMID 32581704, 2020). "Acetylcholinesterase (AChE) and beta-secretase (BACE-1) are the two crucial enzymes involved in the pathology of Alzheimer’s disease." (PMID 32785161, 2020). "A study showed that the BACE1 level is related to mild cognitive impairment (MCI) due to Alzheimer’s disease." (PMID 33192455, 2020). "2,2-Diaryl-2H-imidazol-4-amines are of interest as a BACE-1 inhibitors for the treatment of Alzheimer’s disease or dementia." (PMID 32824981, 2020). "For example, in Alzheimer’s disease PCSK9 plays a direct role in the brain by lowering BACE1 expression and an indirect role by increasing LDL-C levels, which affects Aβ plaque formation and aggregation." (PMID 32595449, 2020). "For instance, a previous study demonstrated that dual BACE-1/GSK-3β inhibitors act through the inhibition of the NQO1 enzyme in order to counteract the oxidative stress in Alzheimer's disease." (PMID 33087132, 2020). "Several studies have shown that targeting BACE1 significantly reduces the presence of β-amyloids, serving as a significant option for an Alzheimer’s disease therapy." (PMID 32515999, 2020). "Systemically administered RVG-EVs loaded with exogenous siRNA produced strong mRNA (60%) and protein (62%) knockdown of BACE1, a therapeutic target in Alzheimer’s disease." (PMID 33271883, 2020). "Next, the group developed a bispecific therapeutic antibody with a low affinity for TfR and a high affinity for the enzyme β-secretase (BACE1), an Alzheimer’s disease drug target." (PMID 31940974, 2020). "Our study suggests that the obtained multifunctional magnetite nanoparticles serve as a vehicle toward effective BACE1 silencing that can be further exploited as gene therapy for Alzheimer’s disease." (PMID 32515999, 2020). "Accordingly, this study aims to develop nanocarriers for targeted delivery of recombinant precursor microRNA (pre-miR-29b), foreseeing a decrease in the expression of the BACE1 protein, with potential implications in Alzheimer’s disease (AD) treatment." (PMID 33076502, 2020). "Cleavage of amyloid precursor protein (APP) by BACE‐1 (β‐site APP cleaving enzyme 1) is the rate‐limiting step in amyloid‐β (Aβ) production and a neuropathological hallmark of Alzheimer's disease (AD)." (PMID 32323475, 2020). "The inhibitory effect of compound 218 was investigated against the action of β-secretase (BACE1), an enzyme strongly correlated with the onset of Alzheimer’s disease." (PMID 33213087, 2020). "The other one is verubecestat (ZINC000144542146), an inhibitor of beta-secretase 1 treating Alzheimer’s disease." (PMID 32218733, 2020). "Since neurotoxic Aβ plays a critical role in Alzheimer’s disease (AD) pathogenesis, BACE1 has emerged as a key target for preventing AD." (PMID 33023225, 2020). "Acetylcholinesterase (AChE) and β-secretase (BACE-1) have become attractive therapeutic targets for Alzheimer’s disease (AD)." (PMID 32899576, 2020). "BACE1, also known as β-secretase 1, is a potential drug target for the treatment of Alzheimer’s disease (AD) due to its involvement in the abnormal production of β-amyloid plaques in AD patients." (PMID 32397127, 2020). "Atabecestat, a potent brain-penetrable inhibitor of BACE1 activity that reduces CSF amyloid beta (Aβ), was developed for oral treatment for Alzheimer’s disease (AD)." (PMID 32410694, 2020).